IL2 (interleukin 2)
Diseases named in the same sentence as IL2 in open-access papers (continued):
Sharing a sentence is not in itself a finding about the gene and the disease.
colon carcinoma (72 papers, 1991 to 2026). "Anti-CTLA-4 combined with EDB-targeted IL-2 caused teratocarcinoma and colon tumor regression to a greater extent when the immunocytokine was injected first." (PMID 33803078, 2021). "Here we show that IL-2-activated NK cells can effectively kill colon carcinoma cells, although the susceptibility of these cells is variable." (PMID 23902851, 2013). "It would be interesting to evaluate the efficacy of cytokine-encoding particularly IL-2-encoding and chemokine-encoding) recombinant H-1PVs in a colon cancer model, too." (PMID 23902851, 2013). "Additionally, in association with parvovirus H-1PV, IL-2-activated NK cells have the potential to boost immune responses against colon cancer." (PMID 23902851, 2013). "Similarly, IL-2 has been associated with the progression of colon cancer." (PMID 37538184, 2023). "We decided to investigate the antitumor activity of IL-2cx (2 μg IL-2/dose) either alone or in combination with ICIs (anti-CTLA-4 plus anti-PD-1 antibodies) using the CT26 mouse colon carcinoma model." (PMID 40789741, 2025). "The effects of targeted M5A‐IL‐2 ICK (ICK) versus untargeted IL‐2‐Fc were compared in a subcutaneous MC38/CEA colon cancer model." (PMID 38317590, 2024). "Subcutaneous growth of tumours (CT26 colon carcinoma model) was also inhibited by our set of fusion proteins, which were more effective than the control proteins containing IL-2 and H9." (PMID 37558752, 2023). "This study tested the efficacy of gene electrotransfer of IL-12 in combination with IL-2 in CT26 mouse colon carcinomas." (PMID 37629081, 2023). "The aim of our study was to determine the effects of gene electrotransfer of plasmids encoding interleukin 2 and interleukin 12 individually and in combination in the CT26 murine colon carcinoma cell line in mice." (PMID 37629081, 2023). "SYBR Green qPCR showed that IL10 and IL12 mRNAs were barely expressed and IL2 mRNA was low, whereas the other ILs were expressed in similar levels to TTP, which were several fold higher than IL2 mRNA in the human colon cancer cells." (PMID 37705049, 2023). "Colon cancer cells treated with 5-FU+IL-2 solution were marked more intensely than the cells in other groups." (PMID 36839637, 2023). "We aimed to assess the efficacy of combining microbial-based therapy using Salmonella SL7207 with interleukin-2 (IL-2), a potent immunostimulatory agent, in the treatment of murine colon carcinoma." (PMID 35962391, 2022). "The addition of tumor necrosis factor α (TNF-α), interferon γ (IFN-γ), and interleukin-2 (IL-2) to human colon cancer cells resulted in the reduced expressions of the cell lines." (PMID 35814435, 2022). "Chemotherapy drugs commonly used in intestinal cancer, such as platinum oxalate, calcium leucovorin, fluorouracil combined with gemcitabine and GM-CSF, IL-2 were used to treat advanced colon cancer." (PMID 36387089, 2022). "Another study showed that IL-2 treatment increased the sensitivity of MDR colon cancer cells to the in vitro application of chemotherapeutic agents." (PMID 35814435, 2022). "In this work, we treated patient-derived colon cancer organoids with IL-2 activated NK-CM (30% final concentration) to explore apoptosis induction." (PMID 35721501, 2022). "The dual delivery of IL-2 and GM-CSF to EpCAM-expressing colon carcinoma in vivo resulted in less lung metastases at low doses, but the effect of the dual immunocytokine was not greater than the single cytokine-carrying molecules." (PMID 33803078, 2021). "SYBR Green qPCR showed that IL10 and IL12 mRNAs were barely expressed and IL2 mRNA was low, whereas TTP and the other ILs were expressed in similar levels, which were several fold higher than IL2 mRNA in the human colon cancer cells." (PMID 33723275, 2021). "Among these compounds, avenacoside A has been shown to inhibit the growth of HCT116 and HT29 human colon cancer cells and decrease the production of intracellular IL-2 in activated T cells." (PMID 31652886, 2019).
colon carcinoma (continued). "Here, the authors design a recombinant vaccinia virus expressing membrane-bound IL-2 that shows therapeutic efficacy alone or in combination with checkpoint inhibitors in colon cancer-bearing mice." (PMID 30410056, 2018). "Soluble colon cancer mucins containing mucins MUC1/2 inhibited IL-2 mRNA expression and secretion of CD4+." (PMID 29661177, 2018). "For example, preclinical studies demonstrated an enhanced antitumor activity of granulocyte–macrophage colony-stimulating factor (GM-CSF) or IL-2 producing murine colon tumor cell vaccines and each cytokine have been used as an adjuvant with cancer vaccines." (PMID 27669687, 2016). "The novel GM-CSF and IL-2 based adjuvant vaccine effectively activated autologous T-cell response and represented a promising immunotherapeutic approach for patients with colon cancer." (PMID 27669687, 2016). "In summary, our data demonstrated that the cytokine (GM-CSF & IL-2) adjuvant vaccine had a significant anti-tumor effect in colon cancer of a mouse model." (PMID 27669687, 2016). "Previous studies showed that a range of cytokines, including interleukin 2 (IL-2), IL-8, IL-10, and insulin-like growth factor 1, inhibited ezrin expression in human colon cancer cells, whereas epidermal growth factor and IL-11 enhanced ezrin expression." (PMID 25915860, 2015). "In the present study we show that IL-2-activated NK cells can effectively kill colon carcinoma cells." (PMID 23902851, 2013). "Altogether, these data suggest that IL-2-activated NK cells actively kill colon carcinoma cells and that this killing is mediated by several natural cytotoxicity receptors (NCRs) in combination." (PMID 23902851, 2013). "To further demonstrate the malignancy of colon tumors developed in Hltf -/-/Apcmin/+ mice, we derived cells from these tumors and then subcutaneously injected them into Rag1-/-/IL2-/- immunodeficient mice." (PMID 22452792, 2012). "For example, IL-2-activated NK cells can kill colon cancer cells effectively." (PMID 38073330, 2024). "Moreover, YRC3780 enhances NK cell activity, which promotes IL-2 production in colon cancer-bearing mice." (PMID 34349248, 2022). "Colon cancer organoids were treated by IL-2-activated NK-CM." (PMID 35721501, 2022). "A combined therapy of ablative radiation dose (20 Gy) with a fusion protein of humanized anti-CEA (carcinoembryonic antigen) and human IL-2 (M5A-IL-2) in a transgenic murine breast and colon tumor model expressing human CEA, had significant antitumor affects as compared with RT alone." (PMID 33806808, 2021). "In the present study, the results showed that JK5G treatment could significantly inhibit the growth of colon tumors, as well as the levels of cytokines in serum, such as IL-2, IL-6, and TNF-α." (PMID 33178591, 2020). "The study of gemcitabine, GM-CSF and low-dose IL-2 combination for treatment of colon cancer patients showed that this regimen had strong immunologic and antitumor activity associated with immunologic events that strongly resembled those induced by cancer vaccine therapy." (PMID 29849947, 2018). "In the present study, we evaluated the efficacy of cytokine adjuvant (recombinant mouse GM-CSF and IL-2) vaccine pulsed with inactivated CT26.WT colon tumor cells via measuring the tumor-specific CTL activity and associated anti-tumor effect in a colon cancer model." (PMID 27669687, 2016). "We show that IL-2-activated human NK cells can effectively kill colon carcinoma cells." (PMID 23902851, 2013). "Combining the expression trends of these genes in colon cancer and after aspirin treatment, we found that aspirin further upregulated NOX4, CXCL8, CXCL5, LIF, GDF15, and MMP13, while stimulated inhibition of IL2, NCF1, and PTGS1." (PMID 41425852, 2025). "Using image-guided RT in a mouse colon cancer model, we observed single high-dose (20 Gy) RT transiently upregulated IL-2Rα (CD25) on effector CD8+ T cells, facilitating the use of CD25-biased IL-2 immunotherapy." (PMID 40502703, 2025).
colon carcinoma (continued). "Here we showed that human IL‐2‐Fc (K35E, C125S in human IL‐2; wild‐type IgG1) with IgG1 Fc effector function is equally efficacious as M5A‐IL‐2 ICK in immunocompetent CEA+ breast and colon cancer models." (PMID 38317590, 2024). "We now compare IL‐2‐Fc to tumor‐targeted M5A‐IL‐2 ICK in CEA+ solid breast and colon cancer models in CEA transgenic mice." (PMID 38317590, 2024). "In a mouse model of colon cancer with human PD-1 and PD-L1, WCC administration reduced tumor growth by approximately 70% and elevated intra-tumoral CD8+ T cells, IL-2, and GrB." (PMID 39771037, 2024). "De Vries and colleagues FACS sorted between 168 and 3775 γδ T cells derived from colon cancer tissue which were expanded for 3-4 weeks using PHA, IL-2 and IL-15, reaching a 2000 to 170.000-fold expansion." (PMID 38426099, 2024). "In a study in the literature, which included the application of IL-2 as monotherapy, immune response was observed in mice with CT26-induced colon cancer." (PMID 36839637, 2023). "When considering the duplication time of 2D colon cancer cells in RTCA, the increase in 5FU/IL2/CD2 nanoplexes was the highest compared with the 5-FU solution, 5-FU+IL-2 solution and other nanoplexes." (PMID 36839637, 2023). "Increased expression of Arg-1 in colon tumor tissue significantly inhibited the secretion of IFN-γ and IL-2 by colon CD8+ T cells." (PMID 36713833, 2023). "A TNF mutant with a reduced potency was generated for an IL-2-TNF dual immunocytokine and controlled tumor progression when targeted to EDA in colon carcinoma, LLC, sarcoma, and teratocarcinoma models." (PMID 33803078, 2021). "Approximately 80% of tumor eradication was seen in colon cancer and sarcoma models when anti-PD-L1 was co-administered with IL-2 or TNF and IL-2 immunocytokines targeted to EDA and EDB." (PMID 33803078, 2021). "Similar to a patient with colon cancer, the stimulation with TKD/IL-2 induced a shift towards the CD3−/CD56bright NK cell subset which was further propagated by nivolumab." (PMID 30747241, 2019). "In a patient with colon carcinoma, repeated infusions of ex vivo TKD/IL-2-activated PBMNC initiate an intrinsic NK cell-mediated cytolytic activity against autologous tumor cells." (PMID 19549307, 2009). "However, CD8+ TILs that have been detected in glioma and colon cancer showed increased activation and cytotoxicity, as indicated by elevated levels of interferon gamma (IFN-γ), tumor necrosis factor alpha (TNF-α), and IL-2 protein or RNA synthesis." (PMID 39537934, 2024). "We showed that IL‐2‐Fc elicits immune memory when combined with SRT in our CEAtg colon cancer mouse model, despite not having the tumor‐specific targeting capability of M5A‐IL‐2 ICK." (PMID 38317590, 2024). "Incubation of CL40 colon cancer cells with IMC-KRASG12D together with HLA-A*11+ PBMC resulted in IMC-KRASG12D concentration dependent IFNγ, IL-2 and Granzyme B release as well as redirected T cell killing in a time- and dose-dependent manner with a mean EC50 value of 28.5 ± 25 pM." (PMID 36088370, 2022). "Other approaches, such as PEGylated IL-2 (NKTR-214) did not achieve similar success when mouse breast and colon cancer tumors were treated as monotherapy." (PMID 34084172, 2021).
colorectal cancer (70 papers, 1990 to 2025). A primary or metastatic malignant neoplasm that affects the colon or rectum. "When we examined pro-tumoral cytokines, such as IL-2 and IL-4, we found that a high colorectal cancer PRS was associated with high IL2 score 21,050,467 (1.09; 1.004–1.18; p = 0.0434) and IL-4 score 21,050,467 (1.12; 1.03–1.21; p = 0.0116) levels in the early stages." (PMID 36428664, 2022). "Almost 4 decades ago, IL‐2 was used with some success to treat cancer, and today, researchers continue to dissect its importance in this disease, with a recent study showing that single nucleotide polymorphisms in the IL‐2 gene are associated with colorectal cancer prognosis." (PMID 32480431, 2020). "A reduced IL-2 may also indicate susceptibility to colorectal cancer." (PMID 33814980, 2021). "CD8+ T cells were first stimulated with magnetic αCD3/CD28 beads and IL2 to become CTLs and then coincubated with murine colorectal cancer cell lines (CT26 or MC38)." (PMID 39292167, 2024). "IL-2 treatment of colorectal cancer patients in a phase I/II peptide vaccination trial observed an expansion of peripheral CD4+CD25highFOXP3+ Treg cells." (PMID 39232704, 2024). "The plasma levels of several cytokines (interleukin-1β /IL-1β/, IL-2, IL-4, IL-10, IL-12, IL-15, TGFβ and IFNγ) of 20 patients with colorectal cancer and 21 healthy individuals were determined by ELISA." (PMID 39456247, 2024). "In this way, it is aimed to increase the T lymphocyte-mediated anti-cancer effect of IL-2 and to develop an effective and reliable chemoimmunotherapy approach in the treatment of colorectal cancer." (PMID 36839637, 2023). "In colorectal cancer patients, the application of IL-2 three days prior to surgery was able to improve overall survival in a phase II study." (PMID 37568571, 2023). "Our group previously reported that radiation plus interleukin-2 suppressed not only local tumor proliferation but also reduced distant metastasis using a mouse subcutaneous colorectal cancer tumor model." (PMID 36653774, 2023). "In colorectal cancer, IL-2 activates TPH1-5-HTP-AhR signaling in the tumor microenvironment to induce CD8+ T cell exhaustion in tumor tissues." (PMID 36703779, 2022). "In line with this phenomenon, previous studies have shown that patients with bladder and colorectal cancer have decreased proportions of IFN-γ/IL-2-producing Th1 cells, while increased proportions of IL-4/IL-10-producing Th2 cells, in peripheral blood." (PMID 29849497, 2018). "A phase I clinical trial has shown that re-infusion of ex vivo TKD/IL-2 stimulated autologous NK cells in patients with late-stage colorectal cancers and NSCLC is feasible, safe, and well tolerated." (PMID 25926832, 2015). "For example, evidence shows that a high dose of dietary vitamin E supplementation in colorectal cancer patients elicits an increase in production of IL2 and IFN-γ by Th1 helper T-cells." (PMID 25072795, 2014). "Treatment of 15 UICC stage IV colorectal cancer patients with IL-2 in a phase I/II peptide vaccination trial further enlarges the already increased naïve Treg-cell pool." (PMID 22276195, 2012). "Expansion of naïve Treg cells was further supported by the increase of TREC numbers that were significantly higher in naïve Treg cells from untreated colorectal cancer patients when compared to healthy controls and further increased post IL-2 treatment." (PMID 22276195, 2012). "Our data indicate that an expansion of CD4+CD25highFOXP3+ Treg cells occurred in the majority of colorectal cancer patients after IL-2 administration as part of combined chemoimmunotherapy." (PMID 22276195, 2012). "In summary, locoregional administration of OK-432 alone and OK-432 plus IL-2 was highly effective for the management of malignant effusion from colorectal cancer." (PMID 14612896, 2003). "Taken together, it is suggested that locoregional administration of OK-432 plus IL-2 is highly effective for the management of malignant effusion from colorectal cancer." (PMID 14612896, 2003).
colorectal cancer (continued). "In the present study, we demonstrated a high efficacy of the locoregional immunotherapy using OK-432 alone or OK-432 plus IL-2 for malignant effusion from colorectal cancer." (PMID 14612896, 2003). "Treatment using a combination of 5-fluorouracil (5-FU), interferon-alpha (IFN alpha-2a) and interleukin 2 (IL-2) has been shown to mediate disease regression in selected patients with advanced colorectal cancer." (PMID 8980407, 1996). "The effects of treatment with 5-FU/folinic acid on interleukin-2 related lymphocyte responses was investigated in 21 patients with advanced colorectal cancer." (PMID 2257211, 1990). "Hence, based on the artificial analysis, we detected critical genes involved in colorectal cancer, including IL-1β, IL-2, CXCL8, and FN1." (PMID 38637796, 2024). "The presence of IL-2 exacerbates the poor prognosis of colorectal cancer patients." (PMID 38967887, 2024). "L. casei BL23 inhibited colorectal cancer growth via the IL-2 signaling pathway." (PMID 37242197, 2023). "Promoting mitochondrial fission enhances the therapeutic efficiency of interleukin 2‐mediated SW480 colorectal cancer cell apoptosis by tanshinone IIA, a chemical compound with cytotoxic and antioxidative effects, thus supporting the concept of fission process induced by chemotherapeutics." (PMID 35318813, 2022). "Despite the paucity of data and clinical limitations, several clinical trials using preoperative low dose recombinant IFN-α and IL-2 have demonstrated less NK- and T-cell suppression and improved prognosis following surgery in patients undergoing colorectal cancer and hepatic metastasis resection." (PMID 30176921, 2018). "In addition, MHC I analysis of colorectal carcinoma tumors in rats that were injected with IL-2 stimulated NK cells showed enhanced MHC I staining in tumor parts closer to NK cell infiltrates." (PMID 26452036, 2015). "We observed significantly higher levels of TREC in Tconv and Treg-cell populations after IL-2 administration suggesting that IL-2 treatment indeed results in a higher thymic output of naïve Treg cells as observed in IL-2 treated human colorectal cancer patients." (PMID 22276195, 2012). "Moreover, after IL-2 treatment of colorectal cancer patients (after treatment), Treg cells had equal suppressive function on conventional CD4+CD25− T-cell proliferation when compared to Treg cells isolated before start of therapy (light grey bar, p<0.001)." (PMID 22276195, 2012). "Irrespective of these experimental differences in earlier studies, we clearly unraveled the expansion of naïve Treg cells to be one of the mechanisms leading to an overall expansion of fully functional Treg cells in colorectal cancer patients which was further augmented by IL-2 therapy." (PMID 22276195, 2012). "In a phase II clinical trial, Correale and colleagues showed that the combination of polychemotherapy with granulocyte macrophage colony-stimulating (GM-CSF) factor and low-dose IL-2 in colorectal carcinoma patients, results in high number of objective responses and low toxicity." (PMID 19272130, 2009). "In total, 16 patients with cytologically proven malignant effusion from colorectal cancer were treated by locoregional administration of the streptococcal preparation OK-432 alone or OK-432 plus the T-cell growth factor interleukin (IL)-2, and the action mechanism of the treatment was studied." (PMID 14612896, 2003). "The clonotypic PCR using the TCRVβ20-CDR3 sequences may be informative for treating malignant effusion from colorectal cancer using OK-432 plus IL-2." (PMID 14612896, 2003). "Based on these data and the correlations with cytokine levels, it can be concluded that CD25, CD80, CD86, CD274 and CD279 glycoproteins combined with specific plasma levels of IL-1β, IL-2, IL-15 and TGFβ could represent potential biomarkers for colorectal cancer." (PMID 39456247, 2024).